ATP1A3 (ATPase Na+/K+ transporting subunit alpha 3)
Description:
Neuron-specific alpha catalytic component of the Na(+)/K(+)- transporting ATPase, which catalyzes the hydrolysis of ATP coupled with the exchange of Na(+) and K(+) ions across the plasma membrane. Transports 3 Na(+) ions out of the cell and 2 K(+) ions into the cell for each ATP hydrolyze against their electrochemical gradients to maintain ion concentration gradients across the membranes (By similarity). In the brain, ATP1A3 is critical for neuronal cell signaling and for maintenance of electrochemical stability, enabling cell excitation and action potential propagation.
Synonyms: AHC2; CAPOS; DEE99; DYT12; RDP
Tractability: Small molecule: an approved drug acts on it; a structure with a bound ligand is known; a high-quality ligand is known; it belongs to a druggable protein family. Antibody: UniProt places it where antibodies can reach, with high confidence; its Gene Ontology location is reachable by antibodies, with high confidence; UniProt predicts a signal peptide or a membrane-spanning region. PROTAC: ubiquitination databases record sites on it; its protein half-life has been measured; a small molecule that binds it is known.
Safety:
Unwanted effects reported when the protein is acted on. In parentheses: how it was acted on, where the effect was seen, and who reports it.
atrioventricular block (inhibition, acute dosing; renal, cardiovascular; source: Lynch et al. (2017))
cardiac arrhythmia (inhibition, acute dosing; renal, cardiovascular; source: Lynch et al. (2017))
decreased heart rate (inhibition, acute dosing; renal, cardiovascular; source: Lynch et al. (2017))
increased cardiac contractility (inhibition, acute dosing; renal, cardiovascular; source: Lynch et al. (2017))
increased urinary sodium excretion (inhibition, acute dosing; renal, cardiovascular; source: Lynch et al. (2017))
increased urine excretion (inhibition, acute dosing; renal, cardiovascular; source: Lynch et al. (2017))
ventricular fibrillation (inhibition, acute dosing; renal, cardiovascular; source: Lynch et al. (2017))
vomiting (inhibition, acute dosing; renal, cardiovascular; source: Lynch et al. (2017))
Gene: Protein-coding gene on chromosome 19 (41,966,582 to 41,997,497, reverse strand). Ensembl gene ENSG00000105409.
Subcellular location: Cell membrane
Pathways (Reactome):
Disease: Potential therapeutics for SARS
Muscle contraction: Ion homeostasis
Transport of small molecules: Ion transport by P-type ATPases
Gene Ontology:
Molecular function: amyloid-beta binding; P-type sodium:potassium-exchanging transporter activity; protein binding; protein-folding chaperone binding; ATP binding; steroid hormone binding; ATP hydrolysis activity; nucleotide binding; P-type potassium transmembrane transporter activity
Biological process: intracellular potassium ion homeostasis; intracellular sodium ion homeostasis; neuron projection maintenance; potassium ion import across plasma membrane; sodium ion export across plasma membrane; cell communication by electrical coupling involved in cardiac conduction; cellular response to amyloid-beta; cellular response to steroid hormone stimulus; proton transmembrane transport; regulation of resting membrane potential; response to glycoside; establishment or maintenance of transmembrane electrochemical gradient; potassium ion transport
Cellular component: axon; endoplasmic reticulum; extracellular vesicle; Golgi apparatus; neuronal cell body; organelle membrane; plasma membrane; sodium:potassium-exchanging ATPase complex; membrane; neuron to neuron synapse; neuronal cell body membrane; photoreceptor inner segment; photoreceptor inner segment membrane; synapse
Genetic constraint (gnomAD): Loss-of-function variants: 12 observed, 112.63 expected, observed/expected ratio (o/e) 0.11, 90% interval 0.067 to 0.17. The upper end of that interval is the gene's LOEUF score, 0.17, which puts it in group 1 of 6, group 1 being the genes least tolerant of losing a copy. Missense variants: 498 observed, 1,450.8 expected, observed/expected ratio (o/e) 0.34, 90% interval 0.32 to 0.37. Synonymous variants: 539 observed, 591.67 expected, observed/expected ratio (o/e) 0.91, 90% interval 0.85 to 0.98.
Gene-disease validity (ClinGen):
ClinGen rates the evidence that ATP1A3 causes each of these diseases.
ATP1A3-associated neurological disorder (autosomal dominant): Definitive. Any neurological disorder in which the cause of the disease is a mutation in the ATP1A3.
Homologues: Orthologues: mouse Atp1a3 (99% identical), rat Atp1a3 (99% identical), macaque ATP1A3 (99% identical), pig ATP1A3 (99% identical), guinea pig ATP1A3 (99% identical), chimpanzee ATP1A3 (99% identical), dog ATP1A3 (96% identical), tropical clawed frog atp1a3 (93% identical), rabbit ATP1A3 (88% identical), Caenorhabditis elegans eat-6 (72% identical), Drosophila melanogaster CG45062 (24% identical), Drosophila melanogaster CG45063 (7% identical). Paralogues in human: ATP1A2 (87% identical), ATP1A1 (87% identical), ATP1A4 (78% identical), ATP4A (65% identical), ATP12A (65% identical), ATP2A2 (30% identical), ATP2B2 (30% identical), ATP2A1 (30% identical), ATP2B3 (29% identical), ATP2B1 (29% identical), ATP2A3 (28% identical), ATP2B4 (28% identical), and 9 more.
Diseases named in the same sentence as ATP1A3 in open-access papers:
ATP1A3 is named in the same sentence as 189 diseases in open-access papers, as found by Europe PMC text mining. Sharing a sentence is not in itself a finding about the gene and the disease. The quoted sentences say what the papers report.
cerebellar ataxia (61 papers, 2014 to 2026). A neurological syndrome characterized by clumsy and uncoordinated movement of the limbs, trunk, and cranial muscles. "The genetic analyses identified spinocerebellar ataxia (SCA) in six families, ataxia-telangiectasia in three families, ataxia with vitamin E deficiency in one family, ATP1A3-associated ataxia in one family, and SPTBN2-associated ataxia in one family." (PMID 40635703, 2025). "More recently, mutations in ATP1A3 have been identified in patients with polymicrogyria, early forms of intellectual deficits with epilepsy and ataxia, childhood-onset schizophrenia, and familial childhood-onset progressive cerebellar syndrome." (PMID 38804677, 2024). "In the first family showing (c.2116G>A) p.Gly706Arg ATP1A3 mutations, the brother and sister presented with severe intellectual deficiency, early-onset drug-resistant epilepsy, ataxia, and autistic features." (PMID 35945798, 2022). "Here we report two cases of infantile‐onset cerebellar ataxia, due to two different ATP1A3 variants." (PMID 32895939, 2021). "Our report contributes to extend the phenotypic spectrum of ATP1A3 mutations, showing paediatric slowly progressive cerebellar ataxia with mild cerebellar atrophy alone as an additional clinical presentation of ATP1A3‐related neurological disorders." (PMID 32895939, 2021). "Recently, some adult patients with rapid‐onset ataxia were reported, and patients with childhood‐onset ataxia‐dominant with ATP1A3 variants were also reported." (PMID 32895939, 2021). "Likewise, PLP1, NKX6-2, and ATP1A3 mutations are linked to spasticity, ataxia, and cognitive deficits." (PMID 41300846, 2025). "The ATP1A3 gene is linked to various neurological disorders, with ataxia occurring in 54% of cases." (PMID 40635703, 2025). "It is commonly believed that pathogenic ATP1A3 variants have resulted in a variety of neurological disorders in the last 20 years, such as rapid-onset dystonia parkinsonism, alternating hemiplegia of childhood, and cerebellar ataxia." (PMID 38022687, 2023). "The ataxia-relevant phenotypes of the eat-6 mutants modelling the ARA-related G316S mutation suggest that C. elegans may be a useful model organism for the in vivo study of other mutations causing ATP1A3-related disorders." (PMID 34612482, 2021). "Genetic diagnoses were more diverse in non-repeat expansion SCA, with pathogenic variants involving 17 genes, the most frequent being ATX-CACNA1A (3 families, 14.3%) and ATP1A3-related ataxia, ATX-ITPR1, ATX/HSP-KCNA2, and ATX-PRKCG (2 families, 9.5% each)." (PMID 39048885, 2024). "Most AHC cases are associated with ATP1A3-related disorders, encompassing RDP, CAPOS syndrome, EIEE, childhood rapid-onset ataxia, and relapsing encephalopathy with cerebellar ataxia." (PMID 39088707, 2024). "More rarely, cases of the Cerebellar Ataxia, Areflexia, Pes Cavus, Optic Atrophy, and Sensorineural Hearing Loss (CAPOS) syndrome related to the ATP1A3 gene have been reported in association with a similar clinical picture." (PMID 40757543, 2024). "ATP1A3 has been implicated aside to AHC syndrome to other complex syndromes including the Rapid-onset Dystonia-Parkinsonism, and the Cerebellar ataxia, Areflexia, Pes cavus, Optic atrophy, and Sensoryneural hearing loss (CAPOS) syndrome." (PMID 35177115, 2022).
cerebellar ataxia (continued). "AR2 (HEXB) had adult-onset ataxia, very prominent oromandibular dystonia and muscle wasting, while AR278 (ATP1A3) had onset at age 11 years, with paroxysmal lower limbs dystonia induced by walking, and progressive ataxia four years later." (PMID 35326432, 2022). "Ataxia is increasingly reported in ATP1A3-related disorders, and thus should be considered a peculiar clinical feature of this condition." (PMID 35945798, 2022). "For example, early infantile epilepsy with encephalopathy (EIEE), recurrent encephalopathy with cerebellar ataxia (RECA), and fever-induced paroxysmal weakness and encephalopathy (FIPWE) are also caused by ATP1A3 mutations." (PMID 33544780, 2021). "This also likely explains why other disorders caused by ATP1A3 mutations, such as rapid onset dystonia parkinsonism (RDP) and relapsing encephalopathy with cerebellar ataxia (RECA) manifest marked bulbar findings of dysarthria, hypophonia, and dysphagia." (PMID 32883312, 2020). "ATP1A3 mutations can also cause allelic disorders such as rapid-onset dystonia-parkinsonism (DYT12, OMIM #128235) and cerebellar ataxia, areflexia, pes cavus, optic atrophy, and sensorineural hearing loss (CAPOS syndrome, OMIM #601338)." (PMID 33126486, 2020). "Of these, 3 variants (p.Val1325Phe in SCN2A, p.Arg756His in ATP1A3, and p.Arg167Met in KCNA1) overlap with those identified from the analysis of the ataxia-related genes identified in Tier-1." (PMID 32466254, 2020). "The affected proteins/disorders included Atp2a2 (Darier’s disease), Eef2 and Itpr1 (Spinocerebellar ataxia), Atp1a3 (Dystonia Parkinsonism)." (PMID 28893375, 2017). "Interestingly, some cases corresponded to channelopathies associated with cognitive and motor delay, in which ataxia has also been described, including KCNC3, ITPR1, ATP1A3 and CTNNB1." (PMID 39048885, 2024). "Two patients carrying different ATP1A3 variants showed slow, continuous cerebellar ataxia without episodic symptoms." (PMID 39088707, 2024). "In the appropriate context, clinicians should screen patients with developmental delay, epilepsy, ataxia, dystonia, and paroxysmal motor signs (positive and negative) for mutations in ATP1A3." (PMID 39712145, 2024). "AR2 (HEXB) and AR278 (ATP1A3), with one patient each, presented ataxia and dystonia." (PMID 35326432, 2022). "In ATP1A3 there are also three fever-induced syndromes, typically with childhood onset: relapsing encephalopathy with cerebellar ataxia, fever-induced paroxysmal weakness and encephalopathy, and cerebellar ataxia, areflexia, pes cavus, optic nerve atrophy, and sensorineural deafness." (PMID 33144327, 2021).
cerebellar ataxia (continued). "It is well known that AHC patients harboring ATP1A3 mutations exhibit various forms of hyperkinetic non-paroxysmal movement disorders as chorea, dystonia, myoclonus, and ataxia, with a heterogeneous degree of severity." (PMID 33897609, 2021). "Although based on only two patients, we believe that the symptoms reported, namely infantile‐onset and slowly progressive cerebellar ataxia, could be a new subtype of ATP1A3‐related neurological disorders." (PMID 32895939, 2021). "The two patients in whom none of the observers had recognized ataxia, were diagnosed with an ATP1A3 and TUBB2A mutation, respectively." (PMID 33255407, 2020). "EA is a clinically heterogeneous disorder characterized by recurrent spells of ataxia lasting minutes to hours which has been associated over time to a number of genes besides CACNA1A and KCNA1 (CACNB4, SLC1A3, FGF14, SLC2A1, ATP1A3, PRRT2) accounting for the majority of cases." (PMID 32823520, 2020). "ATP1A3 mutations are associated with protean manifestations that may include paroxysmal non-epileptic events such as ataxia, dystonia, and paresis." (PMID 39712145, 2024). "ATP1A3 variation is also the primary cause of alternating hemiplegia of childhood (AHC), Relapsing encephalopathy with cerebellar ataxia (RECA), early onset epileptic encephalopathy, and cerebellar ataxia, areflexia, pes cavus, optic atrophy, and sensorineural hearing loss (CAPOS)." (PMID 35978945, 2022). "Finally, patients with mutations in ATP1A3 may also have CAPOS syndrome (cerebellar ataxia, areflexia, pes cavus, optic atrophy syndrome, and sensorineural hearing loss), isolated ataxia or other varied phenotypes." (PMID 33833732, 2021). "ATP1A3-related neurologic disorders have been shown to cause multiple distinct phenotypes: rapid-onset dystonia-parkinsonism (RDP), alternating hemiplegia of childhood (AHC), and cerebellar ataxia, areflexia, pes cavus, optic atrophy, and sensorineural hearing loss (CAPOS) syndrome." (PMID 33544780, 2021). "However, patients with infantile‐onset and pure slowly progressive cerebellar ataxia caused by ATP1A3 variants without any paroxysmal symptoms have not been reported." (PMID 32895939, 2021). "Human mutations in ATP1A3 have previously been discovered in a wide range of autosomal dominant neurological disorders, including encephalopathy with cerebellar ataxia, AHC, rapid-onset dystonia Parkinsonism (ADP), cerebellar ataxia, early-onset epilepsy, and autism spectrum disorder." (PMID 31616254, 2019). "Mutations in the ATP1A3 gene are associated with three related rare neurological disorders, Rapid-onset Dystonia-Parkinsonism (RDP), Alternating Hemiplegia of Childhood (AHC), and recently, Cerebellar ataxia, Areflexia, Pes cavus, Optic atrophy, and Sensorineural hearing loss (CAPOS) syndrome." (PMID 27378932, 2016). "Some of the ATP1A3-related disorders are AHC, rapid-onset dystonia-parkinsonism (RDP), and cerebellar ataxia, areflexia, pes cavus, optic atrophy, and sensorineural hearing loss (CAPOS) syndrome." (PMID 39088707, 2024).
cerebellar ataxia (continued). "Here we report two cases of ATP1A3‐related neurological disorders with infantile‐onset slowly progressive cerebellar ataxia and mild or moderate intellectual disability, but without paroxysmal episodic signs or motor fluctuation." (PMID 32895939, 2021). "In two of these patients (ATP1A3 and TUBB2A gene mutations), ataxia had not been identified." (PMID 33255407, 2020). "In addition, acute-onset choreoathetosis, dystonia and dyskinesia may be encountered in other ATP1A3-related phenotypes, such as recurrent encephalopathy with cerebellar ataxia and CAPOS syndrome (cerebellar ataxia, areflexia, pes cavus, optic atrophy, and sensorineural hearing loss)." (PMID 34204464, 2021).